ENSG00000199815
Gene: Small nucleolar RNA gene on chromosome 3 (8,931,506 to 8,931,631, forward strand). Ensembl gene ENSG00000199815.
Gene Ontology:
Biological process: RNA processing
Cellular component: nucleolus
Homologues: Paralogues in human: SNORA17B (76% identical).